NLRP3 (NLR family pyrin domain containing 3)
Diseases named in the same sentence as NLRP3 in open-access papers (continued):
Sharing a sentence is not in itself a finding about the gene and the disease.
cadmium poisoning (1 paper, 2024). Poisoning occurring after exposure to cadmium compounds or fumes. "The findings suggest that GLP4 reduces cadmium-induced lung injury in mice by inhibiting the activation of the NLRP3 inflammasome, which provides a theoretical foundation for using Ganoderma lucidum as a preventive and therapeutic agent against cadmium poisoning." (PMID 38922058, 2024).
cardiac sarcoidosis (1 paper, 2021). Sarcoidosis affecting the tissues of the heart. "We previously demonstrated the presence of the NLRP3 inflammasome in the granulomas in cardiac surgical tissue of patients with cardiac sarcoidosis, providing additional support for a role of IL-1 in the pathogenesis of cardiac sarcoidosis." (PMID 34749739, 2021).
central obesity (1 paper, 2021). "A gender-specific association of NLRP3 levels with full MetS and its individual components, especially “central obesity” and “low HDL-cholesterol”, was observed only in females in this logistic regression analysis." (PMID 34362072, 2021). "Our data suggest that circulating levels of NLRP3 are positively associated, at least in females, with components of MetS especially central obesity and low-HDL component." (PMID 34362072, 2021). "Logistic regression analysis also yielded a sex-specific positive association of NLRP3 with MetS in females, with this association influenced mostly by central obesity and dyslipidemia components of MetS." (PMID 34362072, 2021).
cerebral aneurysm (1 paper, 2023). "In this study, we tested the effect of NLRP3 inhibition via MCC950 treatment on a mouse model of cerebral aneurysm rupture." (PMID 41541085, 2023).
cerebral tumors (1 paper, 2019). "The implication of NLRP3 inflammasome was reported in several diseases, including ischemia reperfusion injury on the brain, heart, kidney, and testis; neurodegenerative disease; and cerebral tumors as well." (PMID 31847890, 2019).
cherubism (1 paper, 2025). Cherubism is a rare, self-limiting, fibro-osseous, genetic disease of childhood and adolescence characterized by varying degrees of progressive bilateral enlargement of the mandible and/or maxilla, with clinical repercussions in severe cases. "Taken together, these results seem to indicate that our hypothesis of NLRP3/Caspase-1 involvement in the pathogenesis of cherubism is incorrect." (PMID 39951467, 2025).
cholesterol metabolism disorder (1 paper, 2025). "To date, there is little evidence showing LXR inhibition direct activates NLRP3, however, LXR inhibition has been shown to influence NLRP3 by causing cholesterol metabolism disorder or mitochondrial injury and oxidative stress imbalance." (PMID 40778489, 2025).
choroidal neovascularization (1 paper, 2022). An eye disorder described by the growth of new blood vessels that originate from the choroid through a break in the Bruch membrane into the sub–retinal pigment epithelium (sub-RPE) or subretinal space. "A key complication of wet AMD is choroidal neovascularization (CNV), which may be driven in part by NLRP3 inflammasomes that are associated with macrophages migration to CNV lesions." (PMID 36703888, 2022).
chronic nasopharyngitis (1 paper, 2024). "hsa-mir-146a-5p was significantly upregulated in tissues with chronic nasopharyngitis and can target various molecules involved in the NF-κB/NLRP3 pathways." (PMID 39605886, 2024).
CMV pneumonia (1 paper, 2024). "In summary, our findings indicate that mMSC-exo treatment is effective in severe CMV pneumonia by reducing lung inflammation and fibrosis through the NF-κB/NLRP3 signaling pathway, thus providing promising therapeutic potential for clinical CMV infection." (PMID 38675960, 2024).
cocaine addiction (1 paper, 2023). "However, such assumptions about the roles of NLRP3 in cocaine addiction need further investigation and verification by using NLRP3-conditional knockout (KO) mice (microglial-specific KO)." (PMID 37371502, 2023).
cognitive (1 paper, 2025). "Moreover, this memory deficit was rescued with the MCC950 treatment, which indicates that the NLRP3 inflammasome is involved in the development of the cognitive deficits related to PTX chemotherapy." (PMID 40002330, 2025).
colon diseases (1 paper, 2024). "To further explore the effects of NLRP3 deficiency or inhibition on colon diseases, we employed a mouse AOM/DSS-induced colorectal tumorigenesis model." (PMID 39519191, 2024).
colorectal adenoma (1 paper, 2022). An adenoma that arises from the colon or rectum. "Furthermore, 3-(2-oxo-2-phenylethylidene)-2,3,6,7-tetrahydro-1H-pyrazino-[2,1-a], which is a novel small molecular activator of Nrf2, was proven to prevent the development of colorectal adenomas in AOM-DSS models by inhibiting NLRP3 inflammasome activation in the colon." (PMID 36105214, 2022).
communicative disorders (1 paper, 2019). "Thus, OleaVita, which has potential as a supplementation for the inhibition of NLRP3 inflammasomes, may lead to the alleviation of various types of pregnancy complications and non-communicative disorders in humans." (PMID 31035323, 2019).
congenital toxoplasmosis (1 paper, 2017). Toxoplasma infection that is present from birth. "Human susceptibility to congenital toxoplasmosis has also been proved to link to SNPs of NLRP-1; however, the mechanism by which T. gondii activates NLRP3/1-infammasomes is poorly understood." (PMID 28484433, 2017).
contact dermatitis (1 paper, 2021). An inflammatory skin condition caused by direct contact between the skin and either an irritating substance or an allergen. "Our study shows that disulfiram is a potent and dose‐dependent inhibitor of the NLRP3 inflammasome pathway and that topical treatment with disulfiram is effective in inhibiting irritant contact dermatitis." (PMID 34322217, 2021). "The development of novel therapies is a major unmet medical need in contact dermatitis and inhibition of the NLRP3‐inflammasome pathway is a promising approach." (PMID 34322217, 2021).
Corneal opacity (1 paper, 2019). A reduction of corneal clarity. "We employed alkali burn injury and application of lipopolysaccharide (LPS) to induce sterile inflammation of the cornea in wild-type mice and NLRP3 KO (knockout, Nlrp3−/−) mice, and investigated NLRP3-dependent corneal opacity, neutrophil infiltration, and up-regulation of proinflammatory molecules." (PMID 31270454, 2019).
coronary artery aneurysms (1 paper, 2025). "Elevated serum levels of NLRP3 have been reported in KD patients, with significantly higher levels observed in those with coronary artery aneurysms." (PMID 41017238, 2025).
cryptorchidism (1 paper, 2024). The failure of one or both testes of a male fetus to descend from the abdomen into the scrotum during the late part of pregnancy. "The expression of NLRP3 in cryptorchidism leads to an increase in the concentration of inflammatory factors, playing an important role in the apoptosis of GC-1 and TM4 cells." (PMID 39840312, 2024). "This is the first time we found the expression of NLRP3 in cryptorchidism." (PMID 39840312, 2024). "Our experiment first discovered the expression of NLRP3 in cryptorchidism." (PMID 39840312, 2024).
cutaneous lupus erythematosus (1 paper, 2024). An autoimmune disorder that manifests as different lupus-specific skin disorders; it can occur with systemic lupus erythematosus, or as a singular disease. "This study also showed that NLRP1, NLRP3, and ASC were all expressed in the skin of patients that had cutaneous lupus erythematosus as well as in the normal control patients at a lower level." (PMID 39026932, 2024).
dependent (1 paper, 2024). "Genetic ablation of Ncoa6 substantially attenuated the severity of two NLRP3-dependent diseases, folic-induced acute tubular necrosis and crystal-induced arthritis, in mice." (PMID 38195836, 2024).
Dia (1 paper, 2024). "Research has confirmed that NLRP3 inflammasomes play an important role in myocardial cell pyroptosis as well as the occurrence and development of Dia-CM." (PMID 39619569, 2024).
diabetic angiopathy (1 paper, 2025). "In SIRT2-mediated NLRP3 deacetylation, 1,8-cineole is essential for anti-pyroptotic and anti-inflammatory processes with diabetic angiopathy." (PMID 41567643, 2025).
drug-induced liver injury (1 paper, 2022). A spectrum of clinical liver diseases ranging from mild biochemical abnormalities to acute liver failure, caused by drugs, drug metabolites, and chemicals from the environment. "The role of NLRP3 inflammasome in Drug-Induced Liver Injury (DILI)." (PMID 36741414, 2022).
dyslipidaemia (1 paper, 2019). "Similarly, Nlrp3−/− and Asc−/− (Pycard−/−) mice were protected against HFD-induced dyslipidaemia, while WT mice demonstrated significantly elevated triglycerides (TG) and cholesterol plasma levels in response to HFD." (PMID 31379826, 2019).
Dystonia (1 paper, 2019). An abnormally increased muscular tone that causes fixed abnormal postures. "In addition, a severe truncal dystonia was observed in these NLRP3 mutant mice compared with Nlrp3+/+ control mice." (PMID 29786072, 2019).
endolymphatic hydrops (1 paper, 2023). An accumulation of endolymph in the inner ear (labyrinth) leading to buildup of pressure and distortion of intralabyrinthine structures, such as cochlea and semicircular canals. "Sgk−/− mice show aggravated audiovestibular symptoms and enhanced inflammasome activation in lipopolysaccharide-induced endolymphatic hydrops model, which is ameliorated by blocking NLRP3." (PMID 36872329, 2023).
Endometrial Cyst (1 paper, 2022). It is caused by endometriosis, and formed when a tiny patch of endometrial tissue (the mucous membrane that makes up the inner layer of the uterine wall) bleeds, sloughs off, becomes transplanted, and grows and enlarges inside the ovaries. "NLRP3, which is also highly expressed in cultured cells, is continuously activated in clinical conditions due to continued exposure to the contents of endometrial cysts, which can progress to become DAMPs." (PMID 35351143, 2022). "In this regard, NLRP3 is more highly activated in the stressful environment of exposure to the contents of endometrial cysts than in cultured cells, and the therapeutic strategy of inhibiting NLRP3 may be more effective in vivo than in vitro." (PMID 35351143, 2022).
endometrial disorder (1 paper, 2025). A non-neoplastic or neoplastic disorder that affects the endometrium. "Given the key role of the NLRP3 inflammasome in inflammatory endometrial disorders, we investigated the expression of NLRP3 and its downstream effectors, including ASC, Caspase-1, and GSDMD, following exposure to T. pyogenes and MVs." (PMID 40691648, 2025).
endophthalmitis (1 paper, 2022). An infectious process affecting the internal structures of the eye. "Moreover, as neutrophils and retinal microglia-driven NLRP3 activation and IL-1β production play an essential role in murine bacterial endophthalmitis, 3K3A-APC treatment should be considered as a potential treatment for devastating, uncontrolled endophthalmitis." (PMID 36430674, 2022).
Epiphora (1 paper, 2021). Abnormally increased lacrimation, that is, excessive tearing (watering eye). "Immunofluorescence data showed that in GC-1 cells, MEG3 overexpression significantly promoted NLRP3 and caspase-1 expression, indicating that it promoted epiphora, while silencing MEG3 significantly inhibited epiphora." (PMID 34222244, 2021).
Erythema nodosum (1 paper, 2015). An erythematous eruption commonly associated with drug reactions or infection and characterized by inflammatory nodules that are usually tender, multiple, and bilateral. "Also, increased expression of NLRP3 and ASC was observed in 25 BD skin lesions compared to 25 erythema nodosum patients." (PMID 26136643, 2015).
erythroblastic leukemia (1 paper, 2024). "A more detailed analysis revealed that NLRP3 mRNA expression was significantly increased in patient samples categorized as monocytic M4 and M5 FAB subtypes compared to undifferentiated (M0) or erythroblastic leukemia (M6) (data from the NCBI-GEO GSE12417, platform GPL570)." (PMID 39223663, 2024).
extrahepatic cholestasis (1 paper, 2020). Impairment of the bile flow caused by an obstruction in the portion of the bile duct system located outside of the liver. "The extent of inflammasome activation was more or less same in case of both HCMV associated intrahepatic and extrahepatic cholestasis, but the initial activators were different; NLRP3 in case of IHC and AIM2 in case of EHC." (PMID 32985571, 2020).
Fabry disease (1 paper, 2024). Fabry disease (FD) is a progressive, inherited, multisystemic lysosomal storage disease characterized by specific neurological, cutaneous, renal, cardiovascular, cochleo-vestibular and cerebrovascular manifestations. "Targeting the NLRP3 inflammasome and its downstream effects may therefore offer potential therapeutic strategies for managing Fabry disease." (PMID 38932991, 2024).
female infertility (1 paper, 2020). Diminished or absent ability of a female to achieve conception. "Witkin and colleagues showed that a polymorphism in the gene encoding for NLRP3 (CIAS1) is associated with female infertility." (PMID 32047476, 2020).
fibroblast disorder (1 paper, 2017). "Further investigations on the mechanism underlying caspase-1-regulated pyroptosis and IL-18/IL-1β-regulated fibroblast disorder are required to elucidate the function of NLRP3 inflammasome in DCM." (PMID 28790925, 2017).
fracture (1 paper, 2022). "The myocardial activation of the NLRP3 inflammasome, inducing the cleavage mature IL-1β was further shown by our group after multiple trauma and isolated bone fracture, and was also considered to contribute to the development of post-traumatic myocardial damage and secondary cardiac injury." (PMID 36131923, 2022).
gas (1 paper, 2026). "perfringens gas gangrene via enhancing NLRP3 inflammasome signaling." (PMID 41988177, 2026).
generalized epilepsy (1 paper, 2021). Epilepsy that is characterized by generalized seizure types and may have typical interictal and/or ictal EEG findings that accompany generalized seizure types (for example generalized spike-wave). "Baseline gene expression analysis in patients with generalized epilepsy revealed significant activation of gene pathways suggestive of systemic immune activation, such as Rap1 signaling, an upstream regulator of IL-1β production by the NLRP3 inflammasome." (PMID 34208064, 2021).
granulocytosis (1 paper, 2025). "By targeting NLRP3 genetically or pharmacologically in a JAK2V617F mutant mouse model, we formally establish that NLRP3 potently promotes malignant thrombocytosis and, to a lesser extent, granulocytosis." (PMID 41298546, 2025).
hand osteoarthritis (1 paper, 2019). "Meanwhile, results obtained from a study of hand osteoarthritis (HOA) showed NLRP3 protein expression in the peripheral blood mononuclear cells derived from nonerosive HOA patients was much higher compared to that from erosive HOA patients and healthy subjects." (PMID 31870428, 2019).
Headache syndromes (1 paper, 2020). "Headache syndromes were frequently observed among all AID subgroups w/o MS and most commonly found in patients with MEFV- (n = 14; 74%) followed by TNFRSF1A- (n = 5; 63%) and NLRP3 low-penetrance variants (n = 10, 59%)." (PMID 32563262, 2020).
hemorrhagic fever (1 paper, 2024). An infectious disease caused by certain viruses or bacteria that can damage the walls of tiny blood vessels, making them leak, and can hamper the blood's ability to clot and cause severe, life-threatening illness. "It has been reported that infection of SFTSV, another vector-borne bunyavirus that causes hemorrhagic fever, also triggers BAK-dependent NLRP3 activation that is associated with severe disease development and fatal infection in patients." (PMID 39213434, 2024).
Hepatic hemangioma (1 paper, 2025). A congenital vascular malformation in the liver composed of masses of blood vessels that are atypical or irregular in arrangement and size. "Therefore, heme-mediated endothelial cell pyroptosis induces SIRS through the ROS/HMGB1/NLRP3 pathway after RFA of hepatic hemangiomas." (PMID 41280917, 2025).
hepatic veno-occlusive disease (1 paper, 2016). Hepatic veno-occlusive disease (hepatic VOD) is a condition resulting from toxic injury to the hepatic sinusoidal capillaries that leads to obstruction of the small hepatic veins. "On the contrary, the activation of NLRP3 could also lead to inflammatory tissue injury, including intestinal and systemic inflammatory diseases and hepatic veno-occlusive disease." (PMID 27502767, 2016).
herpes infections (1 paper, 2019). "NLRP3 inflammasome has also been the most reported in herpes infections, with consequent Caspase-1 and IL-1β activation." (PMID 31367214, 2019).
Hoyeraal-Hreidarsson syndrome (1 paper, 2022). Hoyeraal-Hreidarsson syndrome (HHS) is a very rare X-linked recessive disorder considered to be a severe variant of dyskeratosis congenita characterized by intrauterine growth retardation, microcephaly, cerebellar hypoplasia, progressive combined immune deficiency and aplastic anemia. "Whether NLRP3 deficiency in Hoyeraal-Hreidarsson syndrome could be a novel component of innate immunity defects remains to be investigated." (PMID 36309505, 2022).
hyperferritinemia (1 paper, 2020). "Taking together all these observations and considering its involvement in AOSD44,45, the direct stimulation of NLRP3 by FeH could provide further insights to the pathogenesis of these diseases, linking the typical hyperferritinemia with the production of a crucial pathogenic mediator." (PMID 32699419, 2020).
hyperparathyroidism (1 paper, 2017). Hyperfunction of the parathyroid glands resulting in the overproduction of parathyroid hormone. "Here, we find that lack of NLRP3 abrogates in vitro osteoclastogenesis induced by bone particles, and more importantly, attenuates bone loss in mouse models of post-menopausal osteoporosis and hyperparathyroidism." (PMID 28747793, 2017).
hypertensive retinopathy (1 paper, 2024). Retinopathy due to hypertension. "SIRT1 adversely regulates the NLRP3 inflammasome pathway, which in turn increases Ang II-induced inflammation and hypertensive retinopathy." (PMID 38360728, 2024). "Our research revealed that Ang II infusion may increase the expression of NLRP3 and reduce the level of SIRT1; these findings showed that Ang II-induced hypertensive retinopathy and dysfunction may involve both SIRT1 and NLRP3." (PMID 38360728, 2024).
Hypervolemia (1 paper, 2020). An increase in the amount of intravascular fluid, particularly in the volume of the circulating blood. "Therefore, we investigated in this cross-sectional observational study the impact of uremic hypervolemia on cytokine activation, with a special focus on NLRP3-dependent IL-1ß activation." (PMID 32138278, 2020). "Although the study clearly shows that hypervolemia does not activate the NLRP3 inflammasome, observational data have been added with regards to the disturbed anti-inflammatory response in H-HD patients." (PMID 32138278, 2020). "The impression that the NLRP3 inflammasome is not activated by hypervolemia is strengthened by data showing that the mRNA level of IL-18, a cytokine which is also regulated by the NLRP3 complex, is not different in H-HD and N-HD patients (H: 1.3 ± 0.6 vs. H: 1.1 ± 0.4, p = 0.222)." (PMID 32138278, 2020).
Hypokalemia (1 paper, 2021). An abnormally decreased potassium concentration in the blood. "Thiazide and loop diuretics are known to induce hypokalemia in vivo, which according to our findings can also enhance NLRP3 activation." (PMID 34315884, 2021).